BRCA1 (BRCA1 DNA repair associated)
Diseases named in the same sentence as BRCA1 in open-access papers (continued):
Sharing a sentence is not in itself a finding about the gene and the disease.
breast cancer (continued). "Here, we generated and characterized Olaparib resistance in BRCA1/2 mutant breast cancer cell lines MDAMB436 and HCC1428 using a systems-level multi-omics approach, including transcriptome, proteome, phosphoproteome, and ADP-ribosylation analysis." (PMID 40669753, 2025). "Drugs like olaparib have shown promise in improving outcomes for individuals with hereditary BRCA1-related cancers, including breast cancer and ovarian cancer." (PMID 39997609, 2025). "Compared to controls, BRCA1/2 carriers had an increased hazard rate for breast cancer before BRRM (HR 7.49, CI 5.81–9.42)." (PMID 40974500, 2025). "To characterize the changes leading to Olaparib resistance in breast cancer cells, we generated Olaparib resistance in Olaparib-sensitive BRCA1 mutant MDAMB436 and BRCA2 mutant HCC1428 cells by culturing them with increasing concentrations of PARPi." (PMID 40669753, 2025). "The GCHBOC is a member of the BCAC (Breast Cancer Association Consortium) and CIMBA (Consortium of Investigators of Modifiers of BRCA1/2) networks, international consortia for hereditary breast cancer." (PMID 41405720, 2025). "Breast cancer incidence increases rapidly in early adulthood until ages 30–40 for BRCA1 carriers and ages 40–50 years for BRCA2 GPV carriers." (PMID 40427184, 2025). "In contrast to ovarian cancers, most functions in BRCA1-mut breast cancer were related to cell damage repair and angiogenesis." (PMID 40647506, 2025). "Fibrillation (FBL) protein, for instance, increases YBX1 binding to the BRCA1 promoter in breast cancer, thereby promoting BRCA1 expression." (PMID 40799245, 2025). "Approximately 70% of breast cancer cases in women are associated with mutations in the BRCA gene family, particularly BRCA1, which serves as a susceptibility gene involved in DNA damage repair pathways." (PMID 41354912, 2025). "Our results suggest a 55–80% likelihood of receiving chemotherapy for BRCA1/2 breast cancer and provide early estimates for patients with PALB2-associated disease." (PMID 40275390, 2025). "The nomogram enables the prediction of the possible 5- or 10-year cumulative risk of CBC for BRCA1 and BRCA2 P/LP variant carriers after their first breast cancer diagnosis." (PMID 39858629, 2025). "Between 2000 and 2024, key terms in the network include breast cancer, growth, DNA methylation, metastasis, proliferation, epigenetics, gene expression, prognosis, BRCA1, tumor suppressor, and epigenetic regulation." (PMID 40978031, 2025). "Of 100 patients, 20% were positive for BRCA1 and 11% for BRCA2 (BRCA: breast cancer susceptibility gene)." (PMID 41020087, 2025). "Genetic predisposition, particularly mutations in Breast Cancer type 1 susceptibility protein (BRCA1)/Breast Cancer type 2 susceptibility protein (BRCA2), significantly increases breast cancer risk (Pal, Das & Pandey, 2024)." (PMID 40034665, 2025). "BRCA1 carriers were predominantly over the age of 40 and typically had a family history of breast cancer (BC)." (PMID 40941635, 2025). "In 2015, studies from the Netherlands, UK, and Canada analyzed 1275 BRCA1/2 carriers with 124 cancers, showing MRI plus mammography combined group reduced breast cancer mortality by 50%–62%, compared to 42%–47% with mammography alone." (PMID 41083355, 2025). "Pathogenic variants in the BRCA1 and BRCA2 genes are associated with increased risk of developing breast cancer." (PMID 40296163, 2025). "A recent large international cohort study assessed the safety of breastfeeding among 178 BRCA1/2 carriers who delivered a child after breast cancer and for whom lactation data were available." (PMID 41302125, 2025).
breast cancer (continued). "Collective evidence thus suggests that estrogen HRT is likely to offer health benefits to perimenopausal or postmenopausal women, including breast cancer survivors, as well as young BRCA1/2 carriers with prophylactic oophorectomy for ovarian cancer prevention." (PMID 39522613, 2025). "Synergism has been observed for triple-negative BRCA1-proficient breast cancer cells treated with anticancer organometallic compounds and other promising inhibitors." (PMID 41155174, 2025). "Further research indicated that daidzein exerts a protective effect against breast cancer by influencing DNA methylation and the expression of BRCA1 and BRCA2 oncogene suppressor genes." (PMID 41226811, 2025). "A retrospective study conducted on a Chinese pan-cancer patient cohort revealed the presence of reversion mutations in three HRR-associated genes: BRCA1, BRCA2, and PALB2, across breast cancer, pancreatic cancer, OC, and lung cancer." (PMID 40166687, 2025). "We retrospectively reviewed treatment administered following a first diagnosis of BRCA1/2- and PALB2-associated breast cancer between 2002 and 2022." (PMID 40275390, 2025). "In breast cancer, HER2 positivity is observed in 2.5% and 3.2% of women with BRCA1 or BRCA2 mutations, respectively, compared to 27.7% and 8.2% for triple-negative tumors." (PMID 39985003, 2025). "This indicates that GNPDA1 is linked to several genes such as BRCA1 and RAD50 and is associated with DNA damage and breast cancer." (PMID 40278313, 2025). "Several nomograms are being developed to predict the future risk of having breast cancer, contralateral breast cancer or EOC in women with gBRCA mutations depending on several factors, one of them being the type of PV in BRCA1/2 gene." (PMID 40714512, 2025). "In mutant BRCA1/2 breast cancers, PARP1’s activity becomes crucial on the basis of defective homologous recombination repair (HRR), creating a synthetic lethal dependence exploited by inhibitors." (PMID 41304924, 2025). "Germline mutations in BRCA1 and BRCA2, which account for roughly 15% of hereditary breast cancer cases, compromise DNA repair mechanisms, leading to genomic instability and increased tumorigenesis." (PMID 40243654, 2025). "Some researchers developed gene-specific predictors for BRCA1 and BRCA2, showing their superiority over genome-wide predictors in evaluating breast cancer-associated variants." (PMID 41263939, 2025). "The median age of breast cancer onset differs significantly between BRCA1 carriers (41 years; range 22–74) compared to WT carriers (48 years; range 27–78; p < 0.001)." (PMID 40422528, 2025). "Mutations in specific genes, such as BRCA1 and BRCA2, are strongly linked to an increased risk of developing breast cancer, as these genes are involved in DNA repair and maintaining genomic stability." (PMID 40531772, 2025). "While SERMs and SERDs remain the cornerstone of ERα-positive breast cancer treatment, BRCA1 mimetics offer a novel approach by targeting tumor suppressor pathways beyond estrogen signaling." (PMID 40283136, 2025). "In the recent CARRIERS study, the prevalence of BRCA1 and BRCA2 mutations in women with breast cancer were 2.14% versus 0.35% in non-breast cancer controls." (PMID 39819384, 2025). "Major traits of metabolic reprogramming were obtained by joint metabolomics/transcriptomics in BRCA1-expressing breast cancer cells." (PMID 40863152, 2025). "This nationwide cohort study provides updated insights into the incidence of unaffected BRCA1/2 carriers, BRRM and RR-BSO uptake, and their impact on breast cancer risk and mortality in Denmark, also compared with the general population." (PMID 40974500, 2025).
breast cancer (continued). "In particular, FOXC1, FOXM1, and FOXO3 can all interact with BRCA1 and regulate the genome stability of breast cancer cells." (PMID 40003882, 2025). "Our in vitro validation showed that Rad51b deletion affects the expression of ERα in mouse Fgfr2-mutant HP5008 cells, Brca1-mutant 545 cells, and the human breast cancer MCF-7 cells." (PMID 41318657, 2025). "Brain metastases in breast cancer patients are particularly concerning and are often associated with HER2 amplification or BRCA1/2 mutations." (PMID 40075655, 2025). "Protein-truncating variants in established susceptibility genes BRCA2, BRCA1, CHEK2, PALB2, ATM and MAP3K1 were associated with a risk of breast cancer, while BARD1 and ATRIP met exome-wide significance for the first time." (PMID 41044259, 2025). "Eight different genes, including ATM, BRCA1, BRCA2, CHEK2, PALB2 (FANCN), RAD51C, and RAD51D, demonstrate significant correlations with an increased risk of breast cancer when harboring pathogenic variations." (PMID 40800071, 2025). "We examined two-hit events of heterochronous bilateral breast cancers in a patient with GDH for BRCA1 and BRCA2." (PMID 40601170, 2025). "Previous studies showed about 21% of HRD predicted TNBC cases to have pathogenic biallelic loss of BRCA1 or BRCA2 and that approximately 81% of these alterations are germline acquired in the general breast cancer population." (PMID 41327380, 2025). "In summary, our study indicated that ISG15 was significantly upregulated in breast cancer, however, its functional role in TNBC specimens with BRCA1 mutation remained elusive." (PMID 40904511, 2025). "By modulating BRCA1, lincRNAs play crucial roles in maintaining genomic integrity and tumor suppression, highlighting their potential as therapeutic targets in breast cancer." (PMID 39997609, 2025). "A genetic predisposition to breast cancer is linked to the BRCA1 and BRCA2 genes, with an ongoing danger of 40–60% in BRCA1 mutation carriers and 13–30% in BRCA2 alterations carriers." (PMID 40141415, 2025). "Given that defects in BRCA1/2 sensitize breast cancer cells to several DNA-damaging agents, we also investigated the correlation between AMH decline during NAC and tumor response to treatment in both gBRCApv and WT patients." (PMID 40220108, 2025). "In contrast, 65% of women carrying a BRCA1 variant and 45% of those with a BRCA2 variant are expected to develop breast cancer later in life." (PMID 40266445, 2025). "One hundred breast cancer patients with BRCA1 methylation were analyzed using pyrosequencing to quantify methylation levels." (PMID 40495194, 2025). "Another patient was found to have a single PV in BRCA1, which explained her young‐onset bilateral breast cancer." (PMID 40936482, 2025). "To this aim, we performed a joint metabolomics/transcriptomics investigation of breast cancer cells expressing BRCA1." (PMID 40863152, 2025). "The study aims to include women carrying a germline P/LP variant (BRCA1, BRCA2, or PALB2), or >5% Tyrer–Cuzick breast cancer risk at ten years, or with a previous diagnosis with intraepithelial neoplasia within the last three years." (PMID 39858629, 2025). "In contrast to BRCA1 mutation carriers, BRCA2 mutated breast cancers have similar pathological features to sporadic breast cancer." (PMID 39621070, 2025). "Another study showed overexpression of YY1 inhibits tumor formation in breast cancer by binding to the promoter of BRCA1 to positively regulate its expression." (PMID 41327312, 2025). "In 2013, a Norwegian study reported the 10 year survival as 69% [95% CI, 48%–83%] for women diagnosed with breast cancer in the annual MRI surveillance program for BRCA1 carriers." (PMID 41083355, 2025). "For instance, hypermethylation of promoter regions in tumor suppressor genes such as RASSF1A and BRCA1 occurs in 40%–60% of breast cancers cases, correlating with advanced stages and poor prognosis." (PMID 40978031, 2025).
breast cancer (continued). "Of participants who satisfied only one of the NDOH criteria (either family history, triple negative breast cancer (TNBC), young age of cancer diagnosis or > 1 primary BC), 11.7% (31/265) had a P/LP variant in BRCA1/2 and 5.1% (12/235) in one of the other BC susceptibility genes." (PMID 39776011, 2025). "This review discusses the mechanisms involving lincRNAs and BRCA1 in breast cancer pathogenesis, highlighting their potential for advancing treatment strategies." (PMID 39997609, 2025). "We have previously shown that mammary epithelial cells and mammary tumors in Brca1 mutant mice at early stages are ER-positive and that the expression of ERα is gradually reduced during cancer progression." (PMID 40157910, 2025). "Polymorphisms in repair genes (BRCA1, BRCA2, CHEK2, XRCC1, XPD) can reduce DNA repair efficiency, leading to genomic instability and increased breast cancer risk." (PMID 40507526, 2025). "Polyphenol-rich extracts downregulate ERα and BRCA1, promote autophagy, and inhibit proteasome activity in breast cancer cells." (PMID 41346617, 2025). "Targeting TUG1 represents a potential therapeutic strategy to restore BRCA1 activity in breast cancer." (PMID 39997609, 2025). "Compared with the matched controls, the breast cancer rate was reduced by a factor of 0.47 (CI 0.12–1.90) after BRRM in the 419 operated BRCA1/2 carriers." (PMID 40974500, 2025). "For example, for breast cancer, international guidelines now classify genes as high (BRCA1/2), moderate (BARD1), and low penetrance (BRIP1) and favor mastectomy for high penetrance but surveillance with magnetic resonance imaging and mammograms for others." (PMID 40282361, 2025). "Patient, tumor, and treatment characteristics at the time of breast cancer diagnosis in BRCA1 versus BRCA2 carriers according to the timing of germline BRCA testing are reported in the Data Supplement (online only)." (PMID 39993249, 2025). "What is the prevalence of BRCA1 and BRCA2 pathogenic or likely (P/LP) variants in an unselected population of women with breast cancer?" (PMID 40952741, 2025). "In agreement with our findings, a metabolomics study identified Ade as a biomarker of the BRCA1 genotype that was significantly increased in wild-type BRCA1-expressing breast cancer cells." (PMID 40863152, 2025). "Mutations in Breast Cancer1/2 (BRCA1/2) are known to be important mechanisms responsible for HRR and are strongly associated with breast cancer risk." (PMID 40510149, 2025). "HRDsig positivity was also detected in 13.1% of cancers with alterations in HRR genes other than BRCA1/2, and 16.5% of breast cancers wild type for all HRR genes were also HRDsig positive." (PMID 40421962, 2025). "Consistent with this, down‐regulation of BRCA1/2 expression induced by PDBAG1 leads to HR repair deficiency, providing an opportunity for the use of PARPis in non‐BRCA mutant breast cancer treatment." (PMID 39748215, 2025). "This means that a BRCA1 and BRCA2 mutation determine a particular change in the probability to develop breast cancer." (PMID 40266445, 2025). "Rutin, identified via computational modeling, exhibits a strong binding affinity to BRCA-1 (breast cancer gene-1), while MO-AuNPs demonstrate potent anticancer activity with an IC50 value of 67.92 μg/mL." (PMID 40149610, 2025).
breast cancer (continued). "The study analyzed breast cancer patients who underwent germline BRCA1/2 testing and received NCT followed by curative resection and standard adjuvant therapy from January 2001 to January 2019." (PMID 40405286, 2025). "Pathogenic variants of BRCA1 and BRCA2 are responsible for approximately 25% of all hereditary breast cancer cases." (PMID 39621070, 2025). "Overall, 309 affected BRCA1/2 and PALB2 carriers with a median age of 43 years at breast cancer diagnosis (range, 19–80 years) were included; 160 (51.8%) BRCA1, 130 (42.1%) BRCA2, and 19 (6.1%) PALB2 carriers." (PMID 40275390, 2025). "An unaffected patient carrying a BRCA1 and MSH6 variants had a family history of breast cancer (case #5)." (PMID 40943312, 2025). "Factors that increase the decision to have BRRM include higher parity, lower age at BRCA1/2 carrier diagnosis, more breast cancer worry, and a history of more affected relatives." (PMID 40974500, 2025). "Established markers for breast cancer cells (BRCA1, MAP3K1, BMPR1A) and fibroblasts (FN1, VIM, COL6A2) were used to classify the clusters." (PMID 39805002, 2025). "A meta-analysis evaluated the association between the incidence of breast cancer and HRT in 1100 women carrying BRCA1 and BRCA2 P/LP variants and intact breasts who underwent bilateral salpingo-oophorectomy (RRSO) before the onset of natural menopause." (PMID 39858629, 2025). "Recent guideline changes have expanded the recommendations for germline BRCA1/2 testing to include women aged ≤ 65 years if they have a history of breast cancer." (PMID 40557948, 2025). "Brca1 deficiency together with ERα signaling enhances SMYD3-SHCBP1 expression, leading to more profound mammary tumor formation in parous mice than virgin mice." (PMID 40157910, 2025). "Germline CNVs overlapping BRCA1 and BRCA2 gene loci associated with the pathogenesis of breast cancer account for less than 5% of known P/LP variants in these genes." (PMID 39858629, 2025). "Ovarian cancer is a lifetime risk of 40%–60% for women who carry hereditary BRCA1 (Breast Cancer gene 1) and BRCA2 (Breast Cancer gene 2) mutations." (PMID 41164269, 2025). "On the other hand, the Breast Cancer Association Consortium studied 4187 women with DCIS and identified a mutation of BRCA1 in 0.24% and of BRCA2 in 0.66% of cases." (PMID 40002208, 2025). "Although male breast cancer accounts for only 1% of all breast cancer cases, it has been linked to HBOC, particularly the BRCA1 and BRCA2 mutations." (PMID 40918841, 2025). "We thus consider that the used breast cancer cell line was representative of general BRCA1-induced metabolic reprogramming." (PMID 40863152, 2025). "All the patients in our study had previously been diagnosed with breast cancer, with an average interval of almost 2 years between their first mastectomy and VAM, and seven of them presented BRCA1/2 mutations." (PMID 40647564, 2025). "In the present study, the uptake rate of BRCA1/2 genetic testing among patients with breast cancer who had undergone fertility preservation was 53.4%." (PMID 40969453, 2025). "For the BRCA1, BRCA2, PALB2, CHEK2, and ATM genes, most protein-truncating variants have been associated with a high risk of breast cancer." (PMID 39858629, 2025). "In fact, BRCA1 and/or BRCA2 mutations account for 5 to 10% of all breast cancers and 20 to 25% of hereditary breast cancers." (PMID 40507272, 2025). "Breast cancer genes 1 and 2 (BRCA1 and BRCA2) are tumour suppressors involved in homologous recombination repair of DNA-double strand breaks, contributing to chemoresistance development when mutated." (PMID 40282556, 2025).